IL10 (interleukin 10)
Diseases named in the same sentence as IL10 in open-access papers (continued):
Sharing a sentence is not in itself a finding about the gene and the disease.
COVID-19 (continued). "As pulmonary fibrosis is also distinctly reported in severe COVID-19 patients, IL-10 supplementation along with other therapy (including MSC-based) may be quite effective." (PMID 35883618, 2022). "Noteworthy, IL-10 is elevated earlier than IL-6 in COVID-19 patients." (PMID 35529862, 2022). "The antiinflammatory cytokine, IL-10 has been identified with protective roles in COVID-19." (PMID 36094915, 2022). "A study that compared the responses in patients with varying severity of COVID-19 and acute dengue infection at different time-points showed significantly higher levels of IL-6, IL-10 and MIP-3α among those who developed COVID-19 pneumonia and DHF than those with mild manifestations." (PMID 35874775, 2022). "Moreover, IL-10 significantly downregulated the spike-induced IFN-γ response in spike-responders of NO-COVID-19-VCs (25/30) [1.39 (0.42-3.11) vs 0.33 (0.12-0.91), p<0.0001]." (PMID 36148228, 2022). "At the same time, other clinical evidence has suggested that early elevation of IL-10 may have a detrimental role in COVID-19 intensity." (PMID 35782361, 2022). "In addition, B cells from acute COVID-19 patients showed increased IL-6 and decreased IL-10 production compared with healthy B cells." (PMID 36357845, 2022). "Among elevated plasma inflammatory mediator levels; CRP, ICAM-1, SAA, VCAM-1, CXCL10, IL-7, IL-10 and Flt-1 may suggest the severity of COVID-19." (PMID 35958594, 2022). "The IL-6, IL-1β, TNF-α, and IL-10 levels were consistently upregulated in patients with COVID-19." (PMID 36230930, 2022). "Growing evidence suggest that severe COVID-19 patients have higher plasma levels of cytokines, such as IL-1β, IL-6, and IL-10, and concentration of these cytokines in the plasma may differentiate mild, moderate, and severe cases." (PMID 36422492, 2022). "Besides IL-6, patients with severe cases of COVID-19 have higher plasma levels of other elements of cytokine storms, including IL-2, IL-7, IL-8, IL-10, and tumor necrosis factor-α (TNF-α)." (PMID 35295802, 2022). "Similarly, increased mRNA expression of IL10 was reported in regulatory T cells of severe COVID-19 patients suggesting a defective adaptive immune response." (PMID 36389738, 2022). "Finally, the high peripheral levels of IL-6 and IL-10 have been highlighted as a predictor of COVID-19 severity." (PMID 36685603, 2022). "The IL-10 effect was observed in both, COVID-19 patients and NO COVID-19-VCs." (PMID 36148228, 2022). "Furthermore, high serum levels of IL-17 and IL-2 and low levels of IL-4 and IL-10 appear to constitute a cytokine profile of long COVID-19, and these markers are potential targets for COVID-19 treatment and prevention strategies." (PMID 35846757, 2022). "Furthermore, data from COVID-19 patients indicated high circulating levels of IL-10 and IL-4, which are protective against inflammation." (PMID 36554094, 2022). "In support, IL-4, IL-5, and IL-10 have previously been shown to increase over the course of disease in patients with severe COVID-19, suggesting an extensive upregulation of the adaptive immunity during COVID-19." (PMID 34987205, 2022). "Interestingly, the finding points at the elevated levels of IL-10 in both COVID-19 as well as DENV infection during the early phases of illness as indicators of altered immune responses possibly lead to severe disease presentation and poor prognosis." (PMID 35874775, 2022). "The relevant role of IL-12 in patients with severe COVID-19 has been described previously in a study showing that interleukin-10 and interleukin-12 levels, in combination with clinical variables, are key biomarkers associated with an increased risk of disease progression." (PMID 36499745, 2022). "This is because IL-10-producing regulatory T cells, which is significant increase in severe COVID-19 patients, might contribute to inhibiting innate inflammatory responses." (PMID 36123740, 2022). "In the severe form of COVID-19, the concentrations of IL-2, IL-6, IL-10, and IFN-γ were elevated." (PMID 35782361, 2022).
COVID-19 (continued). "In severe COVID-19, an early increase in IL-10 concentration was observed." (PMID 35743825, 2022). "Secondly, IL-10 concentrations are elevated earlier than IL-6 in COVID-19 patients." (PMID 36123740, 2022). "Recent studies on COVID-19 suggest that cytokine release syndrome is associated with the severity of disease; this syndrome is characterized by increased TNF-α, interleukin (IL)-6, IL-2, IL-7, and IL-10." (PMID 36361745, 2022). "It is further suggested that IL-10 may be a better marker of the disease conditions because its levels are elevated earlier than IL-6 in patients with COVID-19." (PMID 36233111, 2022). "In COVID-19 patients, it has been suggested that the over-representation of Th17/Treg may affect the levels of regulatory cytokines (IL-4, IL-10, TGF-β, and IL-35) and the ability to tolerate self-antigens, ultimately leading to autoimmune inflammation." (PMID 36034704, 2022). "Indeed, circulating T-regulatory cells, a typical IL-10-producing cell, have been found to be largely increased in abundance in severe COVID-19 despite the concomitant lymphopenia." (PMID 36035415, 2022). "Analysis of an independent cohort of 108 patients from a different center (Cohort 2) demonstrated feasibility of CC/miRNA profiling in leftover hospital blood samples with similar severe disease CC and miRNA profiles, and revealed CCL20, IL6, IL10, and miR-451a as key correlates of fatal COVID-19." (PMID 34957382, 2022). "Moreover, severe COVID-19 patients requiring intensive care in the hospital have high plasma IL-2, IL-7, IL-10, and TNF-α levels." (PMID 36035409, 2022). "In COVID-19, IL-10 levels are increased which promotes neuronal migration." (PMID 36353605, 2022). "PGE2 may participate in the conversion of pro-inflammatory interleukins (e.g., IL-1β and IL-6) to anti-inflammatory interleukins synthesized by M2 macrophages (e.g., IL-10), which may explain the significant increase in IL-10 in patients who survived COVID-19." (PMID 36233111, 2022). "This cell-host interaction is important as many of the cytokines produced in response to COVID-19 (i.e., interleukin-1 beta (IL-1β), IL-2, IL-6, IL-8, IL-10, and tumor necrosis factor alpha (TNFα)) stimulate infiltration of macrophages, monocytes, and neutrophils into the lung tissue." (PMID 35033181, 2022). "However, IL-6 was associated with Lymphocytes (r = 0.59, p<0.05); IL-10 was associated with Eosinophils (r = 0.60, p<0.05); and TNF-ɑ was associated with Basophils (r = 0.56, p<0.05), all in COVID-19 unexposed cases." (PMID 36094915, 2022). "There is also an important number of Th2R and IL-4+IL10+ Tr cells that could explain both the increase of Th2 cells and IL4 and IL10 in severe COVID-19." (PMID 36678366, 2022). "However, the opposite effect, namely decreased levels of IL-4, IL-6, IL-8, IL-10 and IL-17, were observed in convalescent patients after moderate/severe COVID-19, compared to mild convalescents and healthy controls." (PMID 35757700, 2022). "However, the elevated concentration of IL-6 and IL-10 persisted also in recovered post-COVID-19 sera." (PMID 36585712, 2022). "Cytokine storm of interleukin (IL)-2, IL-4, tumor necrosis factor-alpha (TNF-α), interferon-gamma (IFN-γ), and C-reactive protein has not been directly associated with COVID-19, whereas IL-6 and IL-10 were found to be COVID-19 severity predictors." (PMID 35054524, 2022). "Patients who died from COVID-19 stand out for their elevated levels of IL-6, IL-10, and CCL2/MCP-1." (PMID 35336861, 2022). "Increasing evidence supports the elevation of IL-10 is correlated to the severity of COVID-19." (PMID 35493729, 2022). "It has been shown that COVID-19 subjects present elevated Th2-cytokines (IL-4 or IL-10), which could inhibit the Th1 response." (PMID 34967260, 2022). "Results from the BRACE-CORONA trial showed that IL-10 and IL-12 levels could predict the severity of COVID-19 among hypertensive patients." (PMID 36292550, 2022).
COVID-19 (continued). "It was previously shown that the lower levels of IFN-α in the blood of seriously ill COVID-19 patients could be accompanied by elevated levels of pro-inflammatory cytokines (IL-5, IL-6, IL-10, and IL-13)." (PMID 36014561, 2022). "Elevated IL-10 levels in COVID-19 patients may be related to the PD-1/PD-L1 axis in the development of acute viral infections and monocyte rearrangement." (PMID 35971391, 2022). "A recent study proposed that dramatic early proinflammatory IL-10 elevation may play a pathological role in COVID-19 severity as its pro-inflammatory or anti-inflammatory effects that distinguish depending on the different course of disease." (PMID 35493729, 2022). "Administration of recombinant IL-10 has been proposed by some authors for the therapeutic management of ARDS in COVID-19, but clinical evidence has shown that it might be detrimental as it promotes T cell exhaustion." (PMID 35888173, 2022). "This resulted in a model including CCL20, IL6, IL10, and hsa-miR-451a, which was compared to a model with only CCL20 (the most statistically significantly associated factor with fatal COVID-19, adjusted p = 1.02 × 109)." (PMID 34957382, 2022). "IL-10-producing Tregs produce cytokines as an immune-inhibitory mechanism to COVID-19." (PMID 36016311, 2022). "Interestingly, a significant reduction in Treg cells was seen in COVID-19 patients compared to controls, accompanied by a reduction in the Treg transcription factor FoxP3 and a decrease in Treg related cytokines such as IL-10 and TGF-β." (PMID 35572514, 2022). "However, dengue patients who proceeded to develop DHF had several fold higher levels of IL-10 (mean levels 1331 pg/ml) when compared to those who developed severe COVID-19 (mean 57.3 pg/ml)." (PMID 35786403, 2022). "Furthermore, a decrease in serum levels of pro-inflammatory cytokine TNF-α and an increase in anti-inflammatory cytokine IL-10 in patients with COVID-19 following MSC transplantation suggests efficient regulation of cytokine storms." (PMID 36078094, 2022). "Therefore, recombinant IL-10 has been suggested by some investigators for treating acute respiratory distress syndrome (ARDS) in COVID-19 patients based on its immune-regulatory and anti-fibrotic functions." (PMID 35529862, 2022). "Another factor which could help to understand Th imbalance in COVID-19 is IL-10, a potent inhibitor of IL-12 and Th1 response." (PMID 33718270, 2021). "Additionally, high-sensitivity C-reactive protein–albumin ratio (HsCAR) and low prognostic nutritional index (PNI) and the ratio of interleukin (IL)-6 to IL-10 were reported to be related to the prognosis of COVID-19 patients." (PMID 34217339, 2021). "Although IL-10 is a potent inhibitor of LPS-induced gene expression in macrophages, the ability of high concentrations of IL-10 to amplify pro-inflammatory responses to LPS raises the possibility that the combination of elevated IL-10 and bacterial products drives inflammation in COVID-19." (PMID 34234779, 2021). "When we analyzed the immune cells and cytokines between COVID-19 and cancer patients, we discovered that there were similar changes in these biomarkers, such as low lymphocytes, high monocytes, high neutrophils, high IL-6, and high IL-10." (PMID 34712741, 2021). "Many inflammatory factors, including IL-6 and interleukin-10 (IL-10), are closely related to COVID-19 and have diagnostic value, but neither IL-6 nor IL-10 were detected in the patients of this study." (PMID 33534722, 2021). "Interestingly, although with a lesser intensity, the upregulation of AREG, MAFG, MAFK, BCL6 and IL10 still persisted in monocytes of post-COVID-19 subjects." (PMID 34572439, 2021). "In COVID-19, IL-10 could be involved in counteracting the hyperactive immune response, thereby limiting injury but also boosting infection persistence." (PMID 34675240, 2021). "Of course, dynamic changes in serum IL-10 levels may predict different outcomes in COVID-19 patients." (PMID 35126355, 2021).
COVID-19 (continued). "Patients with COVID-19 can also have high levels of IL-8 and IL-10 in CSF." (PMID 34078305, 2021). "An exception may by IL-8 and IL-10, which showed a trend to increase within the first week after COVID-19 diagnosis in the HDx group." (PMID 33808205, 2021). "Of note, IL-10 is significantly upregulated in the most severe forms of COVID-19." (PMID 34359922, 2021). "Although only scarce evidence is available on other Th cell subsets in COVID-19 cases to date, higher blood plasma levels of anti-inflammatory IL-6 and IL-10 related to Th2 subsets, and lower Treg, were reported to be associated with patients requiring intensive care in the hospital." (PMID 33808906, 2021). "In this study, we longitudinally investigated the dynamics of peripheral immune cells and inflammatory cytokines in 67 COVID-19 patients with different disease severities and found that critical cases showed significantly decreased lymphocyte subsets and increased IL-6 and IL-10 levels on admission." (PMID 33461503, 2021). "Both IL-6 and IL-10 are reported to be predictors of COVID-19 severity." (PMID 34384355, 2021). "We detected elevated levels of IL-10 in our group of patients with severe COVID-19." (PMID 34829906, 2021). "Although more investigations are required, it could be hypothesized that treatment with agents increasing IL-10, by reinforcing ACE2 expression or production of Ang 1–7 peptide, may represent a novel way to treat COVID-19-associated ARDS." (PMID 34646263, 2021). "COPD patients with severe COVID-19 had elevated serum levels of various inflammatory cytokines including IL-2R, IL-6, IL-8, IL-10, and TNF-α suggesting there may be global alterations in the immune response." (PMID 34262047, 2021). "The similarity of the IL-10 levels could be due to the early sampling at the hospital admission, its course would be different during the COVID-19 process." (PMID 34384355, 2021). "IL-10 may play a role in COVID-19 disease progression because of its behavior as an immune activating/proinflammatory agent." (PMID 34829906, 2021). "We here retrospectively reviewed the clinical and immunological data of 18 fatal COVID-19 cases, and the results showed that these patients had severe lymphocytopenia together with high serum concentrations of inflammatory cytokines IL-6, IL-8 and IL-10." (PMID 33995382, 2021). "Thus, as a result of high IL-10 levels and the activation of the Th2 pathway, the inflammatory response is reduced, leading to a reduction in severe inflammatory outcomes of COVID-19 in the pregnant population compared to the normal population." (PMID 34682679, 2021). "After adjusting the values for age, sex, baseline situation and COVID-19 severity, IL-10 remained statistically significant (3.3 vs. 2.2 ng/dL, p = 0.042), with a trend towards significance in IL-23 (11.9 vs. 8.6 ng/dL, p = 0.082) and PIGF1 (1621.8 vs. 110.6 ng/dL, p = 0.071)." (PMID 34088273, 2021). "Besides, previous studies demonstrated that interleukin-2R (IL-2R)/lymphocyte, interleukin-6 (IL-6) and interleukin-10 (IL-10) might be the potential biomarkers for early diagnosis and indicators for higher risk of disease deterioration when predicting the disease progression of COVID-19." (PMID 34282057, 2021). "In addition, increased levels of cytokines (e.g., IL-6, IL-10, and TNF-α) have been associated with severe COVID-19." (PMID 34484133, 2021). "Analysis of plasma from patients with COVID-19 has revealed increases in cytokines, including IL-1β, IL-2, IL-6, IL-7, IL-10, TNFα, monocyte chemoattractant protein (MCP1/CCL2), granulocyte colony stimulating factor (G-CSF), and macrophage inflammatory protein 1α (MIP1α/CCL3)." (PMID 34251989, 2021). "As blocking IL-10 function has been shown to prevent T cell exhaustion in animal models of chronic viral infection, thus anti-IL-10 therapy may be useful at the early stage of COVID-19." (PMID 34858428, 2021).
COVID-19 (continued). "Severely ill patients hospitalised with COVID-19 exhibit increased levels of many cytokines, including Interleukin (IL)-1β, IL-2, IL-6, IL-7, IL-8, IL-10, IL-17, granulocyte colony stimulating factor (G-CSF), monocyte chemoattractant protein 1 (MCP-1) and tumor necrosis factor (TNF)." (PMID 34205262, 2021). "Pro-inflammatory cytokines such as interleukin-1 (IL-1), IL-6, IL-8, and tumor necrosis factor alpha (TNF-α) have been found to be elevated in the sera of severely and critically ill COVID-19 patients, anti-inflammatory cytokines such as IL-10 have also been found in the sera of COVID-19 patients." (PMID 34335566, 2021). "On the other hand, high levels of IL-10 and IL-1RA in severe COVID-19 patients can be a signal of an overactive immune response, which may play a detrimental pathological role in COVID-19 severity." (PMID 34858428, 2021). "Importantly, the levels of TNF- α, IL-2R, IL-6, IL-8, and IL-10 were significantly correlated with survival time of cancer patients with COVID-19." (PMID 33735106, 2021). "We here showed that 50.0% (9/18) perished COVID-19 cases have higher level of serum IL-10 than normal values, suggesting IL-10 might also involve in mediating lymphocytopenia." (PMID 33995382, 2021). "The significantly reduced Th and Tc cells and significantly increased IL-6, IL-10, ferritin, procalcitonin, and SAA at this stage in children with critical COVID-19 may be closely associated with the systemic cytokine storm caused by immune dysregulation." (PMID 33865340, 2021). "Importantly, severe cases of COVID-19 are identified as uncontrolled inflammatory response known as cytokine storm where IL-6, IL-1β, IL-10, and IFN-γ have been found to be significantly higher." (PMID 35250966, 2021). "In addition, the levels of IL-6 and IL-10 in SCS COVID-19 patients were significantly higher than that in AS and MS group." (PMID 34118952, 2021). "Thus, we selected IL-6, IL-8, IL-10 and IP-10 as the cytokines with the highest performance in the discrimination of mild COVID-19, severe COVID-19 patients and healthy volunteers." (PMID 34675240, 2021). "Additionally, anti-inflammatory proteins IL-10 and PD-L1 are elevated in healthy males and severe COVID-19." (PMID 34434199, 2021). "We have found fifteen cytokines that remain upregulated in convalescent COVID-19 individuals one month after infection (IL-1α, IL-3, IL-10, IL-12p70, CCL7, IFN-α2, bFGF, LIF, TRAIL, IL-2, IL-4, IL-5, IL-12p40, IL-17 and MIF) indicating a strong activation of the immune response." (PMID 34681885, 2021). "In addition, a follow-up clinical trial including 71 COVID-19 patients (53 mild and 18 severe) from Beijing, China and 18 controls showed that the production of IL-10 in the early stage was significantly correlated with disease severity." (PMID 34234112, 2021). "Patients with COVID-19 have elevated levels of various cytokines such as IL-2, IL-4, IL-6, and IL-10, TNF-α, IFN-γ and may present with the so-called cytokine storm." (PMID 34684384, 2021). "Thus, our findings point to a potentially important role for IL-10 signaling and NK cells in influencing the severity of COVID-19 illness." (PMID 34799557, 2021). "More importantly, critical but deceased COVID-19 patients showed high levels of several proinflammation cytokines, such as IL-2R, IL-8, and IL-6, and anti-inflammatory cytokine IL-10 in vivo, which resulted in lymphopenia, multiple organ failure, and the rapidly decreased nAb response." (PMID 34712742, 2021). "The serum concentration of IL-6, IL-8 and IL-10 might be considered as a reflective sign of the COVID-19 severity." (PMID 33914789, 2021).